ALB (albumin)
Diseases named in the same sentence as ALB in open-access papers (continued):
Sharing a sentence is not in itself a finding about the gene and the disease.
tumor (continued). "The affinity of the probes for albumin was closely related to the kinetic profile of tumor uptake." (PMID 38564087, 2024). "In addition, MKI67, AFP, and ALB level, as well as the immune score, the stromal score, and the tumor purity (estimate score), also showed the similar results to those in TCGA-HCC dataset." (PMID 38374122, 2024). "Breast type, tumor volume, location, histological and radiological features, and localization/surgical duration were evaluated in the context of sentinel lymph node marking using isotope (technetium-99m-labeled human serum albumin) and blue dye." (PMID 39595031, 2024). "Additionally, a nanosystem targeting CD44, composed of d‐α‐tocopherol polyethylene 1000 glycol succinate and CS dual‐modified lipid‐albumin, was found to deliver paclitaxel into multidrug‐resistant tumor cells, thereby overcoming drug resistance." (PMID 38783892, 2024). "These evidences suggest that albumin may inhibit tumor growth and metastasis through antioxidant pathways, thereby improving prognosis." (PMID 38500655, 2024). "In this study, we describe the use of an Flt3L-based immunotherapeutic named albumin-Flt3L (Alb-Flt3L) with potent cross-presenting-DC expansion abilities as an in situ vaccination strategy to promote tumor antigen–specific immunity in combination with standard-of-care chemoradiation." (PMID 37917174, 2024). "Taken together, conjugating PD-L1 aptamer to albumin nanoparticle may prolong its circulation time in vivo, enhance tumor-targeting via the EPR effect, and increase targeting affinity by multivalent binding, resulting in improved antitumor efficacy." (PMID 36985529, 2023). "These may modulate albumin synthesis by hepatocytes and support tumor development by angiogenesis and T-cell suppression." (PMID 37492594, 2023). "In line with these and our observations, somatostatin analogs modified with weaker albumin binders such as the 4-(p-chlorophenyl)butanoate or 4-(p-bromophenyl)butanoate entities showed faster tumor accumulation when compared with the analog modified with the 4-(p-iodophenyl)butanoate entity." (PMID 37686538, 2023). "This suggests that once the complex is delivered to the TME by FcRn- or GP60-based shuttling of receptor-bound albumin across the tumor endothelium, the FHAB : HSA complex is retained in that space by binding to SPARC in a dynamic equilibrium with slow release." (PMID 38250068, 2023). "ALB reflects the malnutritional state of the host and triggers tumor progression and malignancy." (PMID 37566134, 2023). "Tumor tissue has unique properties from those of normal tissue, such as an acidic environment, hypoxia, highly reactive oxygen species, and enzyme overexpression, all of which are fundamental for the study of responsive albumin nanotherapeutic systems." (PMID 38009779, 2023). "Additionally, the circulation time of these compounds seems rather long, probably due to high plasma protein binding (e.g., albumin) which further limits the amount of free tracer available for tumor uptake." (PMID 37894769, 2023). "Due to its configuration, albumin can stably bind different drugs providing great advantages to their pharmacokinetic profile, moreover albumin mediates the drug uptake into the tumor cells by binding over-expressed receptors in tumor or endothelial cells." (PMID 37287910, 2023). "Thus, the risk score (R) was calculated as follow R = 5× (AFP: 0 if <400 ng/ml or 1 if ≥400 ng/ml) + 5× (albumin: 0 if >35 g/L or 1 if ≤35 g/L) + 8× (tumor size: 0 if ≤5 cm or 1 if > 5cm)." (PMID 37434986, 2023). "As well, optimising Nb S1 half-life in serum by fusion with an albumin binder of various affinities could also be an attractive alternative to achieve the best equilibrium between tumour accumulation and high contrast." (PMID 37388728, 2023). "Moreover, a higher tumor burden can increase monoclonal protein production, displacing albumin in the bloodstream and often correlating with more aggressive disease and poorer prognosis." (PMID 37512137, 2023).
tumor (continued). "Second, the PD-L1 aptamer and FEXO carried by albumin nanoparticle may accumulate in tumor tissue due to the EPR effect, enhancing the antitumor effect." (PMID 36985529, 2023). "One possible reason for the decrease in protein accumulation may be a consequence of the tumor cells that use albumin as a source of nutrients (such as amino acids) to support their growth." (PMID 37836018, 2023). "Although PIVKA-II, GGT, and ALB partially reflect different aspects of HCC including tumor burden, vascular invasion, and poor tumor differentiation, respectively, they may complement each other when used in combination." (PMID 37189543, 2023). "Notably, albumin specifically targets tumor regions due to its enhanced permeability and retention (EPR) effect, abnormal nutritional needs, albumin receptor binding, and SPARC-inducing effect." (PMID 37593108, 2023). "Finally, the uptake of extracellular proteins is increased in the tumor, with albumin being the major nutritional source for the tumor." (PMID 37627119, 2023). "The occurrence of tumor-related inflammation can inhibit the synthesis of albumin." (PMID 37836573, 2023). "In parallel, it is known that the inflammation caused by the tumor and the cytokines released secondary to this inflammation reduce blood albumin levels and may thus play a role in tumor progression." (PMID 37685501, 2023). "However, the smaller diameter I-131 radiolabeled Albumin-Paclitaxel NPs following intravenous injection exhibited prolonged blood circulation time and enhanced tumor penetration and uptake." (PMID 37626666, 2023). "Furthermore, bovine serum albumin nanoparticles/si-Nodal nanocomplexes targeting Nodal had anti-tumour effects on CRC progression and metastasis." (PMID 37002201, 2023). "The albumin–cyanine dye complexes, in which albumin serves as an active targeting carrier for the delivery of imaging agents to tumor sites, could be stable in systemic circulation to minimize off-target payload release after systemic administration." (PMID 36614318, 2023). "As a component of the body’s inflammatory response triggered by the tumor, the production of proinflammatory cytokines (such as IL-6) may be a contributing factor to the lower serum albumin concentration." (PMID 37836576, 2023). "The inclusion of features like albumin and absolute lymphocyte count, neutrophil-to-lymphocyte ratio, circulating tumour DNA and protein expression on tumour cells are considered of interest for investigation as co-variables allowing even more precise prognostic prediction." (PMID 37627111, 2023). "Similarly, another PSMA-targeting radioligand ([177Lu]Lu-RPS-63) equipped with the p-iodobenzoate-based albumin binder accumulated faster in the tumor than its analog ([177Lu]Lu-RPS-72) derivatized with a stronger albumin binder." (PMID 37686538, 2023). "Furthermore, serum albumin-coated particles such abraxane are recognised by gp60 receptors on endothelial cells forming neovasculature at tumour sites, thus enhancing localised uptake." (PMID 36842241, 2023). "These vesicles are responsible for transporting albumin within the tumor." (PMID 37836018, 2023). "ALB reflected the nutritional status of patients, which was closely related to tumor progression." (PMID 38041022, 2023). "Considering that white blood cells and albumin reflect the inflammatory response and nutritional status, biomarkers that include these parameters can potentially indicate the characteristics of the tumor and the prognosis of the disease." (PMID 36975410, 2023). "The use of <3 lines, the non-complete and partial response of the first line, modified albumin–bilirubin at grade 2b or 3, an intrahepatic tumor number ≥ 5, extrahepatic metastasis, and alpha-fetoprotein at ≥400 ng/mL were the strongest factors associated with shorter OS." (PMID 37958471, 2023). "The serum level of ALB will be decreased under conditions of inflammation and tumor." (PMID 37089594, 2023).
tumor (continued). "On the one hand, FEXO in albumin nanoparticle may enrich tumor tissue due to the EPR effect, reducing the FEXO dosage requirement." (PMID 36985529, 2023). "Serum albumin is used in the drug delivery mechanism to the tumor." (PMID 36979069, 2023). "Also, they found that the adding of albumin to HCC cell lines significantly inhibited the growth of tumor cells." (PMID 36741016, 2023). "Ongoing clinical studies include trispecifics that target immune checkpoints, three different tumor associated antigens, or two tumor associated antigens and human serum albumin for prolonging the half-life without the Fc fragment." (PMID 37304291, 2023). "Furthermore, rapidly growing tumor cells take up significant amounts of extracellular proteins, including serum albumin, which represents the total volume of extracellular proteins in the tumor cytoplasm." (PMID 37759639, 2023). "Then, we ranked the relative importance of the 40 features and identified the 10 most important predictors, including K, low-density lipoprotein (LDL), D-dimer (D-D), RBC, alanine aminotransferase (ALT), albumin (ALB), monocyte (Mono), tumor size, triglyceride (TG), and age." (PMID 36765583, 2023). "Several studies have reported that albumin, a component of the GNRI, is associated with cancer immunity, as it suppresses excessive neutrophil inflammatory responses or extracellular traps involved in tumor metastasis." (PMID 37968545, 2023). "In our research, age was not identified as a risk factor, nor were other factors such as gender, tumor number, preoperative low albumin, and ECOG physical status that were previously suggested to be correlated with overall survival in patients with HCC-NCL." (PMID 37421456, 2023). "Serum albumin levels may drop due to tumor progression, immune response to tumor and anticancer therapy." (PMID 36941480, 2023). "Furthermore, biomimetic albumin-modified gold nanorods (AuNRs) incorporating paclitaxel (PTX) have demonstrated tumor inhibition through the synergistic effects of photothermal and chemotherapy." (PMID 38258072, 2023). "Inflammatory response and tumor status can affect the concentration of serum ALB, low ALB levels may weaken the immune system, increase the chances of infection, and further accelerate the development of malignant tumors." (PMID 37081512, 2023). "Thus, the exogenous albumin can serve as a versatile carrier for prolonged blood circulation and enhanced tumor accumulation of commercial cyanine dyes, enabling long-term bioimaging and NIR laser-activated cancer phototherapy." (PMID 36614318, 2023). "For these reasons, we postulate that interactions between FOLR2+ TAMs co-localized with Tregs, fetal-like ECs, and ALB+ tumor epithelial cells could be impacted by anti-angiogenic therapies, thereby, potentially impacting immunotherapy response." (PMID 36938978, 2023). "In this study, tumor size (P=0.023), low levels of albumin (P=0.024), lymphocyte to monocyte ratio (P=0.044) were independent risk factors for LNM, with age (P=0.072) and white blood cells (P=0.055) (WBCs) slightly greater than 0.05, probably due to the small sample size in this experiment." (PMID 36761960, 2023). "In conclusion, the fluorinated albumin species have a high potential for 19F MRI tumor diagnostics." (PMID 36838682, 2023). "Hence, the complex of ICG with serum albumin has been increasingly used to improve the blood circulation, photostability, and tumor targeting ability of ICG for clinical and biomedical applications." (PMID 36614318, 2023). "Albumin-bound paclitaxel (nab-paclitaxel), as a special targeted preparation of paclitaxel, has the advantages of good curative effect and less side effects in anti-tumor therapy." (PMID 36859304, 2023). "It was also shown that albumin can inhibit systemic inflammation of tumor progression." (PMID 37875880, 2023). "Those workers were also proved to have high levels of BPDE-albumin adducts and tumor biomarkers." (PMID 36287252, 2023).
tumor (continued). "Besides albumin, bilirubin, tumor number, and tumor diameter, BMD remained an independent prognostic factor in multivariate analysis." (PMID 35986768, 2023). "Thus, albumin-chaperoned cyanine dye reveals enhanced water solubility, biocompatibility, stability, fluorescent brightness, and tumor targetability, satisfying the requirements for the clinical translation of cyanine dyes." (PMID 36614318, 2023). "Moreover, the selective uptake of albumin in tumour and inflamed tissues and its biocompatibility, low toxicity, biodegradability and low immunogenicity make it suitable for systemic in vivo applications." (PMID 37048731, 2023). "In addition, preoperative albumin is an effective factor to reflect the nutritional status and liver function of the patients, and it is also a decisive factor of tumor cell immune response." (PMID 37305570, 2023). "SON-1210 demonstrated robust binding affinity to albumin and exhibited the anticipated in vitro activity and tumor model efficacy that might be expected based on decades of research on native IL-12 and IL-15." (PMID 38250068, 2023). "Hence, the important role of albumin in carrying heptamethine cyanine dyes to the tumor tissue is to improve the water solubility and tumor targetability of the heptamethine cyanine dyes, thereby resulting in increased availability of such cyanine dyes." (PMID 36614318, 2023). "In addition, serum albumin and lymphocytes have also been found to exert anti-tumor effects by enhancing the immune response against tumors." (PMID 36661734, 2023). "The presence of highly expressed proteins, such as albumin in the blood could be obvious interference to identify the tumor-specific proteins with relatively low abundant." (PMID 36759883, 2023). "This is, in turn, supported by reports denoting that albumin NPs induce apoptosis in tumor cells." (PMID 37176983, 2023). "Moreover, proinflammatory cytokines can not only promote tumor invasion but also inhibit the synthesis of albumin and lead to its leakage by increasing microvascular permeability." (PMID 38066499, 2023). "Either tumor cells or TAMs have high demands for albumin as a source of amino acids." (PMID 38258072, 2023). "The dysregulation of cellular recycling of FcRn may explain the increased intracellular uptake of albumin, linking it to metabolic reprogramming, which supports FcRn’s involvement in tumor growth." (PMID 38132243, 2023). "Multifunctional albumin sub-microspheres displayed superior tumor-targeting properties." (PMID 36903477, 2023). "This significantly increases the albumin supply in tumor tissues." (PMID 37836018, 2023). "Albumin and bilirubin provide estimates of the remaining liver function, while the combination of other indicators represents the stage and progression of the tumor." (PMID 36672317, 2023). "Albumin (ALB) is often used as a marker to assess tumor development and prognosis." (PMID 36776604, 2023). "Biodegradability, lack of toxicity, and immunogenicity make albumin an ideal carrier for drug delivery by causing a potential uptake by cells in tumor and inflamed tissue." (PMID 35057002, 2022). "The correlation between serum ALB and tumor prognosis was found in various tumors." (PMID 35663321, 2022). "ALB can effectively reflect the nutritional status of patients, and it is also related to the liver function reserve and release of inflammatory cytokines from tumor cells." (PMID 34997105, 2022). "The mechanism of low serum albumin leading to poor tumor prognosis is complex." (PMID 35729545, 2022). "Furthermore, SPARC proteins (Secreted Protein, Acidic, and Rich in Cysteine) that bind to the albumin-bound drugs in the tumor extracellular matrix contribute to a homogeneous tumor tissue distribution." (PMID 35888170, 2022). "Therefore, as the decline of serum albumin reflects tumor progression through cancer-related inflammation, serum albumin levels are closely correlated with prognosis in patients with cancer." (PMID 35797279, 2022).
tumor (continued). "However, the single level of ALB is often of little significance in clinical application, and the ratio of CRP to ALB was always be used to evaluate the disease status of tumor patients." (PMID 35280511, 2022). "Here, we introduced the albumin binder palmitic acid into the 177Lu-3PRGD2 peptide structure to obtain the long-acting radiopharmaceutical 177Lu-Palm-3PRGD2 and evaluated its therapeutic efficacy in a tumor model." (PMID 35890224, 2022). "Albumin NPs can bind to gp60 receptors on the surface of tumor vascular endothelial cells, resulting in invagination of the cell membrane and the generation of trans-cellular vesicles, which allows the NPs to cross the endothelium and reach the tumor tissue interstitial space." (PMID 35366890, 2022). "Inflammation and tumor formation and development reduce albumin levels, and as albumin decreases, the immune system may weaken and tumor development may accelerate." (PMID 36496365, 2022). "The primary tumor cells were treated with albumin-bound paclitaxel for 72 hours." (PMID 35173526, 2022). "Since it was revealed that tumor tissues extensively uptake plasma proteins, albumin has been intensively studied as a carrier for various anticancer drugs, such as doxorubicin, paclitaxel, gemcitabine, monomethyl auristatin E (MMAE) and camptothecin, due to its abundance in serum." (PMID 35456562, 2022). "As reported in previous studies, the radiolabeled albumin binder may target the tumor because of enhanced permeability and retention of albumin." (PMID 34593598, 2022). "Clinical imaging to quantify tumor vascularization and permeability is available, and clinical albumin imaging agents may identify lesions with heterogeneous albumin extravasation to guide treatment with highly protein-bound drugs." (PMID 35486732, 2022). "Studies have revealed that albumin can inhibit tumour cell proliferation as an anti‐tumour factor." (PMID 35481993, 2022). "Given the role of SPARC in transporting albumin-bound paclitaxel into tumor cells 6, tumoral SPARC may be a more straightforward biomarker for predicting the effectiveness." (PMID 35173526, 2022). "It was also observed that Sgc8-F23 and Sgc8-F20 gradually accumulated in tumors, which might be a competing result between albumin and tumor cells." (PMID 35293579, 2022). "Furthermore, we evaluated the independency of prognostic factors, such as tumor stage, performance status, tumor PD-L1 expression, albumin level, monocyte count, NLR, and the multivariate model." (PMID 35569917, 2022). "We found that systemic injection of miR-329 mimic incorporated into albumin-sericin nanocarriers at therapeutic doses resulted in significant in vivo tumor integration of miR-329 and inhibition of the desired target genes in multiple triple-negative breast cancer (TNBC) models." (PMID 35954481, 2022). "In addition, nab-paclitaxel has targeting properties which, combined with the natural transport mechanism of albumin, allow paclitaxel to act on tumor tissues and achieve higher drug levels within a short period, thereby achieving better anti-tumor effects." (PMID 36406211, 2022). "However, tumor cells adopt a strategy to induce the foci of vascular hyperpermeability in lung ECs, a process that is measured as an albumin flux and that is highly dependent on the EC energy status." (PMID 35628582, 2022). "After adjusting for age, gender, tumor location, tumor size, tumor differentiation, ASA classification, TNM staging, hemoglobin, and albumin, the risk of recurrence in the blood transfusion group was 2.168 times that of the non-transfusion group (HR = 2.168, 95% CI, 1.192–3.943)." (PMID 35937600, 2022). "Additionally, the serum albumin level is correlated with systemic inflammation during tumor proliferation and invasion, stimulates pro-inflammatory factors, and decreases albumin levels by regulating liver cell catabolism and anabolism." (PMID 35909159, 2022).